PSEN1 (presenilin 1)
Diseases named in the same sentence as PSEN1 in open-access papers (continued):
Sharing a sentence is not in itself a finding about the gene and the disease.
frontotemporal dementia (32 papers, 2006 to 2025). Frontotemporal dementia (FTD) comprises a group of neurodegenerative disorders, characterized by progressive changes in behavior, executive dysfunction and language impairment, as a result of degeneration of the medial prefrontal and frontoinsular cortices. "PSEN1 Gly183Val was associated with Pick’s disease and met the consensus criteria for FTD." (PMID 37176125, 2023). "More recently, novel PSEN1 mutations, as well as PSEN1-spliced variants, have been identified in several familiar frontotemporal dementia (FTD) kindreds, suggesting that PS1 may also play a role in FTD pathogenesis." (PMID 16930451, 2006). "The commonly used triple mutant 3xTg-AD mouse model contains two mutations associated with familial AD, APP (KM670/671NL; Swedish), and PSEN1 (M146V), and one with fronto-temporal dementia (FTD), MAPT (P301L)." (PMID 37264120, 2023). "Finally, two mutations in PSEN1 previously -and contentiously- associated with frontotemporal dementia (FTD) (L113P and V412I) were also tested." (PMID 35365805, 2022). "The PSEN1 p.G183V was previously identified in a patient diagnosed with frontotemporal dementia (FTD) and Pick-type tauopathy." (PMID 32917274, 2020). "Mutations in PSEN1 have been implicated in atypical Alzheimer’s disease (AD) and non-AD phenotypes, including frontotemporal lobar degeneration (FTD), Parkinson’s disease (PD), dementia with Lewy bodies (DLB), and spastic paraplegia (SP)." (PMID 40166636, 2025). "We will also discuss the potential mechanisms in which PSEN1 could be involved in other forms of neurodegenerative diseases, including frontotemporal dementia or motor dysfunctions." (PMID 37176125, 2023). "Taken together, PSEN1’s involvement in the formation of frontotemporal dementia/Pick’s bodies remains unclear." (PMID 37176125, 2023). "The Gly183Val mutation in PSEN1 is associated with Pick's disease but not β‐amyloid plaques." (PMID 36223647, 2023). "Two articles study brain tissue of carriers of PSEN1 variants, and one presents a significant upregulation of six genes related to mitochondrial unfolded protein response with primarily differences between primary progressive aphasia (PPA), AD, and a behavioral variant of frontotemporal dementia." (PMID 35959289, 2022). "Genetic susceptibility clearly appears to play an etiologic role for EOD, including APP and PSEN1/2 gene mutations for Alzheimer’s dementia (AD) and MAPT, GNR and C9ORF72 for frontotemporal dementia (FTD)." (PMID 33138082, 2020). "PSEN1 mutations are associated with the phenotypes of familial AD3, familial AD3 with unusual plaques, familial AD with spastic paraparesis and unusual plaques, familial AD with paraparesis and apraxia, frontotemporal dementia, Pick's disease, and dilated cardiomyopathy." (PMID 22482072, 2012). "While mutations in APP, PSEN1, and PSEN2 in the Aβ-generation pathway may lead to familial AD showing plaques and tangles, mutations in MAPT may lead to tangle formation but not plaques, resulting in frontotemporal dementia (FTD) or conditions similar to CBD, PSP, or PiD." (PMID 38732197, 2024). "The most widely used transgenic models express mutant forms of the amyloid precursor protein (APP) gene, with or without presenilin-1/2 (PSEN1/2), which are associated with autosomal-dominant, early-onset AD, or, alternatively, MAPT mutations, which cause familial frontotemporal dementia (FTD)." (PMID 32668255, 2020).
Onset (23 papers, 2011 to 2026). The age group in which disease manifestations appear. "In the majority of familial, early-onset Alzheimer’s, mutations were identified in the genes encoding subunits of the γ-secretase complex – PSEN1 and PSEN2, encoding Presenilin-1 and Presenilin-2, respectively." (PMID 40969213, 2025). "There are two varieties of AD: “early onset forms” (ADAD, less than 5% of all cases) connected to mutations in the presenilin 1/2 (PS-1/2) and amyloid precursor protein (APP) genes and “late-onset AD” (LOAD), the most frequent sporadic form of the illness." (PMID 37371547, 2023). "The remaining 2%–5% of cases are early‐onset AD (EOAD) that are linked to genetic mutation(s) in genes involved in amyloid metabolism, such as Amyloid Precursor Protein (APP), Presenilin 1 (PSEN1), and Presenilin 2 (PSEN2)." (PMID 32857910, 2020). "Both the PSEN1 and PSEN2 variants were found in late-onset PD individuals whereas the GRN variant was found in one control." (PMID 29692703, 2018). "Genetic factors also modulate disease risk: the apolipoprotein E (ApoE) ε4 allele is the strongest known genetic susceptibility factor for late-onset AD, whereas mutations in amyloid precursor protein (APP), presenilin-1 (PSEN1), and presenilin-2 (PSEN2) cause rare familial forms of early-onset AD." (PMID 41373799, 2025). "The genes primarily involved in AD are Amyloid Precursor Protein (APP), Presenilin 1 (PSEN1), and Presenilin 2 (PSEN2), which are associated with early-onset familial AD (fAD), variations in apolipoprotein E (APOE) gene increase the risk of late-onset sporadic AD (sAD)." (PMID 39861466, 2025). "Familial or early-onset AD, which represents less than 5% of all cases, is primarily associated with mutations in genes such as amyloid precursor protein (APP) and presenilin 1 and 2 (PSEN1 and PSEN2)." (PMID 41155642, 2025). "Furthermore, mutations in three common genes—amyloid precursor protein (APP), presenilin-1 (PSEN1), and presenilin-2 (PSEN2) are associated with early-onset AD (EOAD), developing in fourth or fifth decade of life." (PMID 33815092, 2021). "However, three early-onset familial AD genes (APP, PSEN1, and PSEN2) and one genetic risk factor for late-onset AD (APOE) have been identified." (PMID 31080696, 2019). "Early-onset AD is a rare hereditary form of the disease that accounts for ~5-10% of all cases and a minority of early-onset cases has been linked to specific mutations in the genes encoding amyloid precursor protein (APP), presenilin 1 (PSEN1), and presenilin 2 (PSEN2)." (PMID 34712240, 2021).
Parkinsonism (23 papers, 2008 to 2025). Characteristic neurologic anomaly resulting from degeneration of dopamine-generating cells in the substantia nigra, a region of the midbrain, characterized clinically by shaking, rigidity, slowness of movement and difficulty with walking and gait. "In the context of Parkinsonism, cognitive decline commonly manifests as the primary symptom in the majority of PSEN1 mutations, with Parkinsonism emerging in the later phases of the disease." (PMID 38339035, 2024). "PSEN1 variants have been reported to have a pleiotropic effect in Parkinson’s disease, another neurodegenerative disease that has also been demonstrated to be influenced by PSEN1 variants." (PMID 38790243, 2024). "Although overt parkinsonism is associated with PSEN1 mutations, the underlying pathomechanism is unclear." (PMID 37648940, 2023). "Several PSEN1 mutations were associated with motor impairment, including spastic paraplegia, Parkinsonism or myoclonus." (PMID 37176125, 2023). "Heterozygous mutations in PSEN1 (p.Phe105Leu, p.Met146Val, p.Glu280Ala, p.Leu286Val, p.Leu392Val) are responsible for familial AD, with parkinsonism mainly appearing in advanced stages." (PMID 37648940, 2023). "While frequently observed in late phases, parkinsonism at onset with mainly axial phenotype and presenile dementia has been associated with specific PSEN1 mutations (p.Gly217Asp and p.Val272Ala)." (PMID 37648940, 2023). "These variants have been detected in 2 patients who presented the typical hallmarks of PSEN1 mutations: early onset of symptoms, aggressive symptomatology, and extrapyramidal signs (parkinsonism and myoclonus)." (PMID 24880964, 2014). "Parkinsonism was also common hallmark of EOAD with PSEN1 mutations." (PMID 37176125, 2023). "In the majority of PSEN1 mutations, the initial symptoms may be cognitive decline, and Parkinsonism occurs in later disease stages." (PMID 37176125, 2023). "In the last decade the number of PSEN1 mutations discovered has increased; complex neurological phenotypes such as seizures, myoclonus, spastic paraparesis and ataxia, in variable associations with cognitive impairment and parkinsonism, have been reported." (PMID 37648940, 2023). "Interestingly, a novel PSEN1 mutation was recently identified as the likely cause for early‐onset parkinsonism." (PMID 33433033, 2021). "However, Parkinsonism could also be an initial symptom in cases of several PSEN1 mutations, mutations such as Arg41Ser, Gly217Asp and Val272Ala." (PMID 37176125, 2023). "Genetic mutations and protein abnormalities linked to diseases like Alzheimer’s (APP, PSEN1, PSEN2), Parkinson’s (PINK1, LRRK2), and Huntington’s (HTT) can be detected in fibroblasts, reflecting similar changes in brain pathology." (PMID 39766775, 2024). "Parkinsonism should be carefully investigated, especially why in some disorders or specific genotype (e.g. SCAs, POLG-related ataxias, some PSEN1 mutations, SPG7) a good levodopa response has been reported." (PMID 37648940, 2023). "Among known amyloidogenic genes potentially leading to parkinsonism, PSEN1 is the most epidemiologically relevant." (PMID 37648940, 2023). "In our study, we now demonstrate that HSV-1 infection induced a broad and complex transcriptional response in both WT and PSEN1/2 mutant COs, deregulating genes significantly involved in pathways related to neurodegeneration, including Alzheimer’s, Parkinson’s, and prion diseases." (PMID 40661646, 2025). "Interestingly, PSEN1 Gly417Ala was found in a 37-year-old male patient diagnosed with symptoms that overlap between AD and Parkinsonism, followed by progressive language disturbance and behavioral changes with Parkinsonism." (PMID 31182772, 2019). "We were specifically drawn to a group of genes that were significantly dysregulated in blood and brain, including Necab3, Apbb2, App, Psen1, Saa1, Prkcg, Park2, Snca and Prnp, because of their involvement in neurodegenerative diseases, such as Alzheimer’s and Parkinson’s disease." (PMID 24278249, 2013).
Parkinsonism (continued). "However, its connection to several query genes (Tbp and Mapt) and to several proteins functionally related to the query set (Mdm2, Fyn, Psen1, Apoe, Uchl1, and Dbh) in mouseNET suggests its potential role in Parkinson's disease." (PMID 18818725, 2008). "The mechanism of how PSEN1 may be involved in Parkinsonism remain unclear." (PMID 37176125, 2023). "Several PSEN1 mutation carriers did not present classical EOAD phenotypes, but other neurodegenerative diseases, such as FTD (such as Leu113Pro and Thr122Ala), DLB (such as Glu184Asp and Ala275Ser), PD, Parkinsonism, spastic paraparesis (such as Arg41Ser and Glu120Lys)." (PMID 37176125, 2023).
Spastic paraparesis (20 papers, 2014 to 2025). Partial loss of the ability to move the lower limbs accompanied by spasticity of the lower limbs. "As can be seen with other PSEN1 mutations, carriers of these mutations often present with spastic paraparesis in the lower extremities, which progresses over time to affect the upper extremities in the advanced stages of the disease." (PMID 39800455, 2025). "While our review focused on its association with isolated spastic paraparesis (SP) at onset, a broad spectrum of clinical phenotypes has been linked to PSEN1 mutations, ranging from neurodegenerative disorders to dermatological conditions." (PMID 40943910, 2025). "Our study also supports the correlation between PSEN1 mutations associated with spastic paraparesis and cotton wool plaque pathology, which in turn has been shown to correlate with cerebral amyloid angiopathy in some, but not all, cases." (PMID 38824433, 2024). "In this paper, we describe a family with a particularly young onset of spastic paraparesis due to a novel mutation in PSEN1 (F388S)." (PMID 36895955, 2023). "Spastic paraparesis has been described to occur in 13.7% of PSEN1 mutations and can be the presenting feature in 7.5%." (PMID 36895955, 2023). "Here, for the first time, we have defined the consequences of the PSEN1 E280G mutation, which is associated with atypical clinical (spastic paraparesis) and pathological features (amyloid plaques of the cotton wool type)." (PMID 36687397, 2023). "Of note, the analysis of PSEN1 variants presenting additionally with spastic paraparesis, indicates that a different mechanism underlies the aetiology of this distinct clinical phenotype." (PMID 35365805, 2022). "The c.851C>T (p.Pro284Leu) carriers developed spastic paraparesis (SP), which is an atypical form of AD occasionally associated with certain PSEN1 mutations." (PMID 35260199, 2022). "For instance, spastic paraparesis affects 45% of PSEN1-A431E mutation carriers and is reported as an early feature of the PSEN1-G266S mutation." (PMID 35365805, 2022). "Widespread white matter abnormalities have been shown to associate with PSEN1 mutation-related spastic paraparesis and the degree of WMH has positive correlations with the severity of CWP." (PMID 30090657, 2018). "We have observed abnormalities in white matter indexed using diffusion tensor imaging in association with spastic paraparesis among carriers of the A431E PSEN1 mutation, potentially indicating the involvement of processes to some extent unrelated to Aβ or neurofibrillary pathology." (PMID 39800455, 2025). "Together, these findings support the hypothesis that PSEN1 P436S mutations cause fAD, with observed atypical features in some individuals including late spastic paraparesis." (PMID 38824433, 2024). "The pathophysiology of spastic paraparesis in PSEN1‐associated fAD is not well understood and may relate to altered processing of γ‐secretase substrates other than APP." (PMID 38824433, 2024). "In addition to the EOAD phenotypes, several different symptoms were related to PSEN1 mutations, including myoclonus, seizures, extrapyramidal symptoms, spastic paraparesis and behavioral and language dysfunctions." (PMID 37176125, 2023). "A novel PSEN1 p.Arg278Gly pathogenic variant was found in an AD African ancestry family (mother and four sons) presenting with progressive spastic paraparesis starting in their fourth decade and followed within months by progressive non-fluent aphasia (and later frontal dysexecutive dysfunction)." (PMID 37712079, 2023). "It was reported that PSEN1 mutations occurring after codon 200 were more frequently associated with spastic paraparesis and visuospatial impairment as well as an earlier AOO, while mutations before codon 200 were more frequently associated with seizures and myoclonus." (PMID 37051054, 2023).
Spastic paraparesis (continued). "The characteristic phenotype associated with a PSEN1 mutation probably represents the syndrome of “variant AD,” which is most often associated with mutations around exon 8 and characterized by early-onset familial dementia and spastic paraparesis." (PMID 24955352, 2014). "Familial AD patients with spastic paraparesis are likely to have a PSEN1 mutation while familial AD patients with cerebral hemorrhage caused by cerebral amyloid angiopathy may have APP mutations." (PMID 24955352, 2014). "Diffusion tensor imaging (DTI) analyses of PSEN1 A431E variant carriers with spastic paraparesis showed widespread white matter abnormalities that were not confined to the corticospinal tract, suggesting an effect of the PSEN1 A431E variant on white matter integrity in the brain." (PMID 38801124, 2024).
memory impairment (19 papers, 2013 to 2026). "Memory impairment is a key feature in PSEN1 mutation carriers, with both verbal and visual memory severely affected." (PMID 40649976, 2025). "PSEN1 pathogenic variant carriers had a variable clinical presentation, including memory impairment, behavioral changes, language, and extrapyramidal symptoms consistent with what we know about PSEN1 mutations." (PMID 35932032, 2022). "A novel mutation in exon 5 of presenilin-1 (Thr119Ile) in a Korean patient with EOAD who showed memory decline at 64 years of age followed by memory impairment, language problems, and personality changes." (PMID 31182772, 2019). "In a triple transgenic mouse model (mutations in the APP, presenilin 1 (PSEN1) and TAU genes), the deletion of CB2 induces AD-like TAU pathology and memory impairment." (PMID 34001284, 2021). "We also demonstrated that injecting SPON1 reduced the amount of Aβ and ameliorated cognitive dysfunction and memory impairment in 5xFAD mice expressing human APP and PSEN1 transgenes with five AD-linked mutations." (PMID 32455709, 2020). "PSEN1 c.617G > A, p.Gly206Asp was discovered in a female patient who showed memory impairment at age 33 and later had seizures." (PMID 33188256, 2020). "Furthermore, an NMR-based metabolomics study of the transgenic amyloid precursor protein/presenilin 1 (APP/PS1) mouse model of Aβ pathology found that these mice had significant hypothalamic metabolic abnormalities prior to memory impairment." (PMID 30568576, 2018). "Notably, patients in prodromal phases of AD show memory impairments, depression, anxiety and reduction of olfaction function, as we observed in APP/PSEN1-Tg mice at 3 and 6 months of age." (PMID 33795014, 2021). "First, prior to appreciable neurodegeneration, CBP is downregulated in the absence of presenilin 1 (PS1) and 2 (PS2) concomitantly with a reduction in the expression of CREB-dependent target genes and memory impairment." (PMID 23448461, 2013).
neuroblastoma (19 papers, 2010 to 2024). Neuroblastoma (NB) is the most common solid, extracranial childhood tumor. "In N2a mouse neuroblastoma cells expressing APPswe with either WT PSEN1 or PSEN1 deletion (PSEN−/−), trafficking of APPswe was altered by PSEN1 deletion, indicating roles for γ-secretase in addition to processing." (PMID 39302110, 2024). "In experiments where neuroblastoma cells were cultured under low folate and vitamin B12 conditions, PSEN1 and BACE1 were hypomethylated, mRNA expression of BACE1 and PSEN1 was significantly induced, and Aβ production was increased." (PMID 24877062, 2014). "SK-N-SH neuroblastoma cells were transduced with vectors expressing mutations in genes that are found in FAD: human APP with both K670N/M671L (Swedish) and V717I (London) mutations (APPSL) as well as presenilin 1 with the ΔE9 mutation (PSEN1ΔE9)." (PMID 37739965, 2023). "However, whereas neuronal activity does not affect Psen1 mRNA levels in cortical neurons, glutamate and BDNF activate Psen1 expression in a CREB-dependent manner in neuroblastoma cells." (PMID 29269871, 2017). "Moreover, SAM administration in human neuroblastoma SK-N-SH cell cultures resulted in downregulation of PSEN1 gene expression and Aβ peptide production." (PMID 21119889, 2010). "Reducing folate and vitamin B12 uptake in neuroblastoma cell lines diminishes SAM levels and reduces methylation in promoter regions of beta-site amyloid precursor protein cleaving enzyme 1 (BACE1) and presenilin 1 (PSEN1) genes." (PMID 35053330, 2022). "In murine neuroblastoma cells Neuro2a overexpressing the mutant APPswe (N2a/APPswe), CUR treatment decreased the expression of presenilin-1 (PS1; γ-secretase) and beta-site amyloid precursor protein cleaving enzyme 1 (BACE-1; β-secretase), proteases involved in the synthesis of Aβ plaques." (PMID 27110749, 2016).